HGF (hepatocyte growth factor)
Diseases named in the same sentence as HGF in open-access papers (continued):
Sharing a sentence is not in itself a finding about the gene and the disease.
autism (9 papers, 2009 to 2024). Persistent deficits in social interaction and communication and interaction as well as a markedly restricted repertoire of activity and interest as well as repetitive patterns of behavior. "Researchers examined the association of EGF, TGF-β1, and HGF genes with autism in a trio association study using DNA samples from families recruited to the Autism Genetic Resource Exchange." (PMID 25729218, 2015). "The molecular mechanism by which mutations found in the Met gene become causative for characteristics seen in autism and autism spectrum disorder should be further addressed, but the neuro-developmental role of the HGF–Met pathway may be somewhat altered by these mutations in the Met gene." (PMID 28548072, 2014). "Phenotypic characteristics caused by impaired MET/HGF signalling such as modified neuronal migration and disrupted neuronal growth in the cortex, as well as a decreased proliferation of granule cells causing a parallel reduction in the size of the cerebellum, have been seen in the autism patients." (PMID 22110649, 2011). "Continued investigations of clinical populations will be needed to determine the contribution of lower concentrations of HGF to the etiology of the complex phenotype of autism." (PMID 20029653, 2009). "The HGF–Met pathway contributes to the development of the cerebral cortex and the cerebellum, both of which exhibit developmental disruptions in autism." (PMID 28548072, 2014). "The MET gene located in the region was considered a good candidate both because of the biological importance of the MET/HGF signalling pathway in autism aetiology and also because of the successful association of MET variants with autism in previous studies in European and Japanese populations." (PMID 22110649, 2011). "Although hypothetical, deficiency in either HGF or c-MET could initiate and promote a sustained immune response consistent with chronic features of autism pathophysiology, and could therefore be an important contributor to the autism phenotype." (PMID 20029653, 2009). "Increased risk for autism, due to a functional polymorphism in the MET gene, and lower levels of unbound HGF, may impart, particularly in individuals with severe GI disease, shared etiology of a parallel, although independent, disruption of brain and peripheral organ development and function." (PMID 20029653, 2009). "In this study, concentrations of EGF and HGF were assessed in the plasma of 49 children with ASD aged 2–4 years old and 31 typically developing controls of a similar age as part of the Autism Phenome Project (APP)." (PMID 22937258, 2012). "It was reported that hepatocyte growth factor (HGF) is down-regulated in the serum of ASD children, so it is considered that serum HGF concentration might be a biomarker of children with autism." (PMID 32824515, 2020). "Their results revealed a significant haplotypic association between EGF and autism, but no significant SNP or haplotypic associations were observed for TGF-β1 or HGF." (PMID 25729218, 2015). "On the other hand, an increasing body of evidence shows that the HGF-MET axis is involved in a spectrum of neurological processes, including axonal growth, glutamatergic circuit development, synaptic plasticity, physiological learning and memory, and in a neuropathological syndrome, such as autism." (PMID 36139568, 2022).
autoimmune disease (9 papers, 2006 to 2025). A disorder resulting from loss of function or tissue destruction of an organ or multiple organs, arising from humoral or cellular immune responses of the individual to their own tissue constituents. "Hepatocyte growth factor (HGF) has been investigated as a regulator for immune reactions caused by transplantation and autoimmune diseases and other biological functions." (PMID 35889092, 2022). "HGF has been reported to have immunosuppressive effects on reactions caused by transplantation and autoimmune diseases." (PMID 25889917, 2015). "It has been demonstrated that HGF reduces inflammatory Th1 cells via dendritic cells and stimulates regulatory T cells to produce immunosuppressive cytokines which are beneficial in the treatment of autoimmune diseases." (PMID 35231072, 2022). "Because the perforin/granzyme B pathway has been implicated in potential mechanisms of oligodendrocyte and/or axonal injury and demyelination in MS, our findings together suggest that increased HGF may reduce CTL effector function in CTL-mediated human autoimmune disorders of the CNS." (PMID 32075650, 2020). "MSCs can exert their immune function and relieve autoimmune diseases through PEG2, TGF-β, HGF, IL-10, and IDO, which are found in RA, IBD, and other autoimmune diseases." (PMID 33859701, 2021). "Thus, it appears that HGF inhibited lupus-like autoimmune disease through the inhibition of Th2 generation rather than by induction of Th1." (PMID 16859527, 2006).
cerebral infarction (9 papers, 2019 to 2023). An ischemic condition of the brain, producing a persistent focal neurological deficit in the area of distribution of the cerebral arteries. "In HD patients, higher levels of HGF are associated with concentric left ventricular geometry and cerebral infarction." (PMID 35453489, 2022). "When exogenously applied in vitro, HGF enhances synaptic long-term potentiation (LTP) in the CA1 region of the hippocampus, and overexpression of HGF in vivo improves memory and learning after cerebral infarction in rats." (PMID 36538176, 2023). "In a cerebral infarction animal model, HGF exerted neuroprotective effects and promoted angiogenesis without exacerbating the cerebral edema, and thus reduced the ischemic damage." (PMID 30823442, 2019). "Moreover, BMSCs-HGF decreased HIBD-induced cerebral infarction volumes and enhanced the protective effects of the BMSCs against HIBD." (PMID 35003786, 2021). "Furthermore, in a model of cerebral infarction, HGF gene transfer resulted in enhanced neurite extension and functional recovery." (PMID 34955750, 2021). "Furthermore, overexpressing HGF during the chronic stage of cerebral infarction promotes neurite outgrowth and synapse formation, contributing to improvements in learning and memory." (PMID 30823442, 2019). "Our immunohistological analysis revealed that HGF exogenously administered into the damaged spinal cord increased the number of newly formed vessels 1 week after injury onset, confirming that HGF enhanced the angiogenic activity, as seen in the cerebral infarction animal models." (PMID 30823442, 2019). "HI insult induced brain infarction (82.45% ± 5.91%), while the infarct volume was significantly reduced in the BMSCs-GFP and BMSCs-HGF groups, respectively (both P < 0.001)." (PMID 35003786, 2021).
glaucoma (9 papers, 2011 to 2024). Increased pressure in the eyeball due to obstruction of the outflow of aqueous humor. "The aim of our study was to investigate the association between tag SNPs of the HGF gene and primary angle closure glaucoma in the Nepalese population." (PMID 21897747, 2011). "Genetic variation in the hepatocyte growth factor (HGF) gene has recently been associated with hyperopia, which is a known risk factor for primary angle closure glaucoma (PACG)." (PMID 21897747, 2011). "Interestingly, in the Nepalese population HGF was recently reported to be associated with primary angle-closure glaucoma, in which patients were usually featured by shorter axial length and vitreous chamber depth." (PMID 22509107, 2012). "This study aimed to investigate whether genetic variation in HGF is associated with primary angle closure glaucoma in the Nepalese population." (PMID 21897747, 2011). "The MR analysis genetically predicted that the levels of six distinct circulating inflammatory cytokines might be causally linked to the risk of these blinding eye diseases, including MIG for glaucoma, IL-1ra, IL-6, IL-10 and PDGFbb for cataract, and MIG and HGF for macular degeneration." (PMID 38327497, 2024). "Because HGF and NGF both play important roles in the treatment of ocular nerve injury diseases (e.g., corneal damage and glaucoma), we hypothesized that HGF and NGF also play important roles in tissue repair during the prophase and postoperative recovery phase of IMHs." (PMID 33430811, 2021). "The aim of this study is to examine whether or not hepatocyte growth factor (HGF) genetic variations are associated with susceptibility to primary angle-closure glaucoma (PACG) in the Han Chinese population." (PMID 23585864, 2013). "Using ELISA, multiple growth factors including hepatocyte growth factor (HGF) and TGF-β2 have been shown to be increased in the AH of patients suffering from glaucoma." (PMID 30673862, 2019). "Expression of proteins enriched in the vitreous (CCL2, IGFBP2, MMP10, HGF, TNFRSF11B (OPG)) was localized by immunohistochemistry in eyes of patients with severe ischemic CRVO followed by secondary glaucoma." (PMID 25978399, 2015). "This supports the finding of Hu and Ritch that increased HGF concentration in aqueous humor of glaucomatous eyes possibly reflects the functional effects of HGF on enhancement of aqueous flow and attempt to repair trabecular injury, rather than directly causing glaucoma." (PMID 21897747, 2011).
Hepatitis (9 papers, 2012 to 2023). Inflammation of the liver. "In contrast, recombinant HGF inhibited CLP-associated hepatitis in rats." (PMID 22536224, 2012). "HGF was found to be well correlated with the severity of hepatitis and its prognosis in this study, with the group with high HGF and high RIPK3 having a high probability of death." (PMID 37640752, 2023). "It was reported that HGF restrains hepatic injury, conferring protection from hepatitis and fibrosis." (PMID 25970780, 2015). "Liver HGF expression increased markedly after various liver injuries such as hepatitis, ischemia, physical crush and partial hepatectomy." (PMID 23951204, 2013). "We provided the first evidence that recombinant HGF enhanced hepatic regeneration in mice with hepatitis." (PMID 23296269, 2013). "However, at the critical 3 dpi timepoint when most C57BL/6 mice succumbed to hepatitis, nearly all measured C57BL/6 analyte levels were highly elevated including IL-6 and HGF, two inflammatory markers associated with the liver." (PMID 35834486, 2022). "In this study, it demonstrated that BCL6B may play a pivotal role in the process of hepatitis development through upregulation of HGF, but the exactly mechanism needs further investigation." (PMID 25970780, 2015). "Based on this background, we demonstrated in the late 1990s that a forced increase by supplemental therapy with HGF could prevent LPS-induced hepatitis." (PMID 22536224, 2012). "Toxin-induced hepatitis becomes severer in NK2-transgenic mice, suggesting an antagonistic effect of NK2 (i.e., release of HGF-mediated hepatic protection)." (PMID 23296269, 2013). "As for serum HGF levels, there was a significant increase consistent with the severity of hepatitis (non-SH: 0.8 ± 0.7 ng/mL, SH: 2.1 ± 1.4 ng/mL, ALF: 4.6 ± 2.6 ng/mL, P < 0.01)." (PMID 37640752, 2023).
limb ischemia (9 papers, 2014 to 2024). A ischemia that involves the limb. "A study carried out on patients with PAD provided evidence that the levels of angiogenic factors, particularly vascular endothelial growth factor and hepatocyte growth factor, escalates with the severity of limb ischemia." (PMID 38606780, 2024). "Previous studies revealed that VEGF-A combined with HGF resulted in a potent angiogenic effect in a mouse model of limb ischemia." (PMID 35012671, 2022). "In our previous work, using a mixture of pDNAs bearing each factor (VEGF165 or HGF) alone, we found that equimolar production was a prominent feature of this method and resulted in an impressive increase in efficacy in a limb ischemia model." (PMID 33353116, 2020). "Our previously published data showed that in animals with limb ischemia combination of VEGF and HGF-encoding pDNAs resulted in enhanced angio- and arteriogenesis in skeletal muscle compared to each factor alone." (PMID 29787588, 2018). "In preclinical animal models for limb ischemia, intramuscular administration of either recombinant HGF protein or expression plasmid for HGF has facilitated collateral new vessel formation, improved blood flow, and reduced muscle atrophy." (PMID 28548072, 2014). "In a mouse model of limb ischemia, bFGF was found to directly stimulate the expression of HGF mRNA through the p42/44 MAPK pathway in the early stage, and to indirectly induce HGF expression by stimulating the secretion of endogenous PDGF-AA in the later stage." (PMID 39291265, 2024). "The developed vector provides an attractive option for further development to address unmet medical needs—limb ischemia, peripheral neuropathy and other diseases that can be relieved by effects of HGF and VEGF165 on vascular and neuronal trophic in impaired tissues." (PMID 33353116, 2020). "Overall, our study reports a first-in-class candidate gene therapy drug to deliver two pivotal angiogenic growth factors (HGF and VEGF165) with properties that provide basis for future development of treatment for an unmet medical need—peripheral artery disease and associated limb ischemia." (PMID 33353116, 2020). "Current study reports on experimental development of a candidate pDNA-based drug to express HGF and VEGF165 in mammalian tissue and evaluation of its therapeutic efficacy in a mouse model of limb ischemia." (PMID 33353116, 2020).
lymphoma (9 papers, 1999 to 2025). A malignant (clonal) proliferation of B- lymphocytes or T- lymphocytes which involves the lymph nodes, bone marrow and/or extranodal sites. "Additional eight mutations that were significantly enriched in rHL/prHL affect genes that were previously associated with the progression of other lymphoma subtypes (e.g., PDGFRB, KAT6A, HGF, EPHB1, NSD2, PMS2)." (PMID 39992429, 2025). "In this study, we aim to further test the robustness of using IGF2 and HGF to replace FF in this lymphoma mouse model and to investigate the role of microenvironment and estrogen signaling in tumor development." (PMID 34539876, 2021). "The same weekly injection of IGF2, HGF, and their combination induced lymphomas in 4/11 (36%), 3/8 (38%), and 6/9 (67%) mice, respectively." (PMID 34539876, 2021). "There are only limited data studying the role of HGF/c-MET signaling pathway in lymphomas, when compared to those from other solid tumors." (PMID 27923392, 2016). "In the current review, we summarize recent findings about the expression, cellular mechanisms/functions, and therapeutic application of HGF/c-MET in different types of lymphoma, especially B cell lymphoma, T and NK cell lymphoma, and Hodgkin lymphoma." (PMID 27923392, 2016). "In contrast to other solid tumors, there are limited data describing the functional role of HGF/c-MET signaling pathway in lymphoma." (PMID 27923392, 2016). "We also discuss the existing problems and future directions about studying the HGF/c-MET pathway in lymphoma cells." (PMID 27923392, 2016). "However, compared to other solid tumours, there are limited data on the role of the HGF/c‐Met signalling pathway in lymphomas." (PMID 34651428, 2021). "However, few studies about the role of HGF/c-MET signaling pathway in lymphoma, a group of lymphocyte-derived cancers, have been documented." (PMID 27923392, 2016). "HGF increased the adhesion of c‐Met‐positive B cell lymphoma cells to fibronectin and collagen that was mediated via β1‐integrin, which may suggest why HGF/c‐Met‐positive lymphomas have a poorer prognosis." (PMID 34651428, 2021). "Therefore, future work highlighting more potential mechanisms of activating HGF/c-MET signaling from lymphoma cells may uncover innovative therapeutic strategies for these malignancies." (PMID 27923392, 2016). "Previous studies have reported that the elevated plasma HGF levels serve as a prognostic factor in AML patients Similarly, patients with lymphoma exhibit increased HGF levels in their blood, bone marrow, plasma, and pleural fluid." (PMID 40520181, 2025). "PCR analysis of clonal rearrangement of the TCRβ gene locus demonstrated that all four (FF, IGF2, HGF, HGF+IGF2) induced lymphomas, like the spontaneous lymphomas grown at old age, had a prominent monoclonal Dβ-Jβ rearrangements." (PMID 34539876, 2021). "In this review, we will discuss the role of HGF/c-MET pathway in the pathogenesis of lymphoma cells and potential therapies for different types of lymphoma, based on recent published data." (PMID 27923392, 2016). "Specifically, the FF-induced lymphoma, its transplant, and a spontaneous lymphoma showed Dβ1Jβ1 recombination (left), whereas the IGF2-induced lymphoma, its transplant, HGF-induced lymphoma, IGF2+HGF-induced lymphoma, and another spontaneous lymphoma showed Dβ2J2 rearrangement (right)." (PMID 34539876, 2021). "Among lymphomas, the HGF receptor is predominantly expressed in diffuse large B-cell lymphoma (DLBCL), and interestingly, DLBCL cells also express HGFA, possibly activating HGF produced by macrophages in the tumour microenvironment." (PMID 18691255, 2008).
lymphoma (continued). "We assessed the effect of human HGF/SF on the dissemination of the B-lymphoma cells and found that administration of 5 μg HGF/SF to mice, injected (i.v.)with c-MET-positive lymphoma cells, significantly (P = 0.018) increased the number of metastases in lung, liver and lymph nodes." (PMID 10487611, 1999). "In addition, HGF/SF did not significantly influence dissemination of c-MET-negative lymphoma cells (P = 0.350 with Daudi cells and P = 0.353 with Ramos cells)." (PMID 10487611, 1999). "Thus the effect of administration of HGF/SF on invasion of lymphoma cells is not an indirect one, e.g. via an effect on endothelial cells." (PMID 10487611, 1999). "However, currently, there are no HGF inhibitors that have been tried in lymphoma treatment, so here, we will focus on c-MET inhibitors, their application in lymphoma treatment." (PMID 27923392, 2016). "HGF influenced the metastasis of c-MET-positive cells into multiple organs, including the liver, kidney, lymph nodes, lung, gonads, and the central nervous system, in SCID mice but did not affect metastasis of c-MET-negative lymphoma." (PMID 27923392, 2016).